PARP1 (poly(ADP-ribose) polymerase 1)
Diseases named in the same sentence as PARP1 in open-access papers (continued):
Sharing a sentence is not in itself a finding about the gene and the disease.
cancer (continued). "We analyzed the 12 DisGeNET-identified genes in selected human cancers with cBioPortal in order to identify any correlation between gene expression and PARP1 in selected human cancers." (PMID 31105872, 2019). "One drawback of cancer treatment with PARP1 inhibitors is the onset of resistance that often occurs." (PMID 31105872, 2019). "Although some PARP-1 inhibitors have been reported, their clinical application in cancer therapy is limited by some shortcomings such as weak affinity, low selectivity and adverse side effects." (PMID 31766720, 2019). "In view of the important therapeutic value of PARP-1 inhibitor for cancer and potentially for AD treatment, it was interesting and deserved to further explore structural optimization of Olaparib based on the existed SAR." (PMID 30427217, 2019). "In contrast, at higher concentrations than those causing PARP1 inhibition, PJ34, Tiq-A and Phen eradicate a variety of human cancer cells by ‘mitotic catastrophe cell death’." (PMID 31692907, 2019). "This study has shown that it is feasible to utilize in silico screening approaches to rationally design PARP-1 inhibitors with possible utility in the treatment of cancer." (PMID 31766720, 2019). "As we found BBR didn't change PARP1 expressions but affect the cellular free PAR, we over‐expressed PARP1 in cancer cells to detect the cell growth after treatment with BBR." (PMID 31338966, 2019). "Mortaparib inhibits mortalin and PARP1 resulting in activation of growth arrest and apoptosis signaling in cancer cells in vitro and in vivo." (PMID 31856867, 2019). "The success of synthetic lethality with PARP1 gave hope for the development of highly personalized therapies that take into consideration the molecular uniqueness of each cancer case." (PMID 31615159, 2019). "In light of the information that overexpression of mortalin and PARP1 promotes cell migration, invasion and angiogenesis, we next asked if inhibition of mortalin and PARP1 by Mortaparib was sufficient to block these phenotypes of cancer cells." (PMID 31856867, 2019). "Olaparib, a PARP1 inhibitor, was developed for the treatment of cancers with defects in DNA repair, especially tumors with BRCA mutations." (PMID 31113933, 2019). "In our review, we will discuss recent findings highlighting the composite multifaceted role of PARP-1 in cancer and inflammation-related diseases." (PMID 31877876, 2019). "Given the highly important role of PARP1 in DNA repair and cancer intervention, this structure presents an attractive opportunity to explore the therapeutic potential of PARP1 inhibition via G-quadruplex DNA targeting." (PMID 30551210, 2019). "MacroH2A1.1 is a potent transcriptional modulator associated with favorable outcomes in several solid tumor types, restriction of cancer stem-cell emergence, and PARP1 (Poly (ADP-ribose) Polymerase-1)-dependent chromatin remodeling." (PMID 31439048, 2019). "Consistent with the role of mortalin and PARP1 in cancer cell migration, metastasis and angiogenesis, Mortaparib-treated cells showed inhibition of these phenotypes." (PMID 31856867, 2019). "The PARP-1/2 inhibitor Olaparib (OLA) is approved by FDA to treat certain patients harboring cancers with impaired homologous recombination." (PMID 30691122, 2019). "Here, we focused on the poly (ADP-ribose) polymerase 1 (PARP1) gene and its interaction network, because PARP1 inhibition is widely used in cancer therapy." (PMID 31105872, 2019). "PARP1 in rapidly dividing cells facilitates the expression of genes that confer a cancer cell phenotype." (PMID 31614656, 2019). "Mechanistically, defining PARP-1 dependent DNA processing functions is pivotal for the development of successful PARPi therapy and therapeutic regimens in the treatment of different cancers." (PMID 31877876, 2019). "Until now, most studies have focused on PARP-1, initially as an enzyme involved only in DNA repair, but subsequently also in apoptotic and necrotic cell death and in cancer." (PMID 31130919, 2019).
cancer (continued). "The role of PARP-1 inhibitors in decreasing DNA damage repair and promoting synthetic lethality in BRCA-mutated cancer is already well known." (PMID 31303961, 2019). "BRCA1 is a suppressor gene, whose dysfunction is linked to a higher risk of developing cancer, such as inhibition of DNA repair enzymes poly (ADP-Ribose) polymerase 1 (PARP1)." (PMID 31540486, 2019). "We here intend to review the main roles of PARP-1 in DNA repair and inflammation, and the pathological involvement of this multifaceted molecule in cancer and inflammatory-related diseases." (PMID 31877876, 2019). "A series of new Olaparib derivatives was designed and synthesized, and their inhibitory activities against poly (ADP-ribose) polymerases-1 (PARP-1) enzyme and cancer cell line MDA-MB-436 in vitro were evaluated." (PMID 30427217, 2019). "Based on the mechanism of PARP1-H2AX-BRCA1/2, recent study has focused on PARP1 as a possible therapeutic target for various human malignant tumors, especially in carcinomas have defects in BRCA1/2." (PMID 29784019, 2018). "Given that PARP‐1 activity is enhanced as a function of aggressive disease, patterns of HR gene expression were queried in human cancer." (PMID 30467127, 2018). "The overexpression of PARP1 has been observed in several types of human cancers and plays important roles in carcinogenesis and cancer development." (PMID 29776974, 2018). "It has been shown that PARP1 has been considered as a putative initiator of cancer and that inhibition of PARP1 in HepG2 cells transfected into nude mice prevents liver cancer." (PMID 30271949, 2018). "To highlight the utility of this approach, we describe its application to study resistance to the anti-cancer drugs camptothecin or olaparib, leading to the identification of various mutations in yeast TOP1 and in mouse Parp1, respectively." (PMID 29670134, 2018). "We here show that PARP-1 has also a preponderant role in the death of lymphocytes induced by H2O2 in the cancer and Ca&AD groups." (PMID 29472838, 2018). "PARP1 was also shown to co-operate with nuclear receptors (estrogen, progesterone and androgen receptors) in cancer cells." (PMID 29306194, 2018). "Due to their synthetic lethal relationship, in HR-defective BRCA1/2-mutant cells, that is, cancer cells, chemical inhibition of PARP-1 is selectively toxic in combination with conventional chemotherapy." (PMID 30200453, 2018). "The rationale was that pharmacological inhibition of PARP-1 function in rapidly dividing cancer cells would result in an accumulation of single-strand breaks leading to broken replication forks that are essentially DSBs." (PMID 29998112, 2018). "These novel findings have the potential to impact cancer therapy, based on the discovery that PARP‐1 suppression has the capacity to induce or enhance BRCA‐ness through regulation of DNA repair factor availability." (PMID 30467127, 2018). "The relatively fast proliferating cancer cell line (A549) used in this study is positive for both PARP1 and RB1 (as confirmed by western blots – PARP1 and chromatin immunoprecipitation in G1 arrested cells – RB1)." (PMID 29306194, 2018). "Phosphorylation of p38MAPK, which usually occurs in response to oxidative stress, was also increased in cancer cells when PARP1 was inhibited." (PMID 29684820, 2018). "Taken together, our results indicate that PARP1/Ku80/Ku70 complexes activate cancer-specific genes via binding to ALCDs." (PMID 30271949, 2018). "Disruption of the ATM-PKM2-CtIP axis sensitizes cancer cells to a variety of DNA-damaging agents and PARP1 inhibition." (PMID 30297868, 2018).
cancer (continued). "Genetic deficiencies, together with the action of DNA-damaging chemotherapies, render cancer cells more dependent on PARP-1 and PARP-2 for DNA repair and therefore more sensitive to PARP inhibition." (PMID 29527010, 2018). "The data presented are impactful in cancer, as PARP‐1 activity is increased as a function of disease progression and is associated with poor outcomes." (PMID 30467127, 2018). "As PARP1 is increasingly attracting the attention as promising drug target for cancer therapy, we focused on the effect of PARP1 on Nurr1-mediated gene regulation." (PMID 29738496, 2018). "In case of functional defects of both HR and classical NHEJ, inhibition of PARP1 avoids activation of Alt-EJ and cancer cells undergo apoptosis." (PMID 30518089, 2018). "PARP1 inhibitors have been effective radio-sensitizers for prostate and other cancers by furthering DNA damage accumulation." (PMID 29717261, 2018). "To help address this deficiency, we utilized gene editing to construct genetically-null PARP1 human cancer cells." (PMID 30410680, 2018). "Olaparib is one of the PARP1 inhibitors used in the treatment of gynecologic and other cancers; however, standard chemotherapeutic agents remain a mainstay of therapy as well." (PMID 29783721, 2018). "Data herein indicate that PARP‐1 positively regulates E2F1‐mediated HR gene expression in cancer, and that suppression of this activity can potentially induce a “BRCA‐ness” phenotype." (PMID 30467127, 2018). "PARP1 hyperactivation has also been shown to occur when DNA repair is defective, as in XPA-deficient cells, XRCC1 mutant individuals and in HRR-defective cancer cells." (PMID 29684820, 2018). "When using cancer cells with stable knockdown of PARP1, which form much smaller tumors, a significant rescuing effect by NOX1/4 depletion was detected." (PMID 29684820, 2018). "PARP1 is frequently upregulated in many cancers; therefore, blocking its activity using small molecules has great therapeutic potential." (PMID 29757235, 2018). "In all, these results support the idea that in Ca&AD and cancer lymphocytes, oxidative stress induces death that is markedly PARP-1 dependent." (PMID 29472838, 2018). "Identification of PARP‐1 as a regulator of E2F1 transcriptional function in PCa, specifically with regard to regulation of HR gene expression, sheds new light as to the molecular impact of PARP‐1 function in cancer." (PMID 30467127, 2018). "For example, talazoparib is 100-fold more potent at trapping PARP1 on DNA and >50 fold more potent at killing cancer cells than rucaparib and olaparib, although the apparent IC-50’s for all three compounds are quite similar (1–5 nM)." (PMID 30088474, 2018). "A literature and COSMIC search revealed that several of these mutations have been detected in other model systems and other cancer subtypes, e.g. PARP-1 (V377S), ATR (K297 N), FANCA (G809 N), and MLH3 (I541V)." (PMID 30305041, 2018). "The role of PARP1 in DNA damage response has been well studied and the protein has been extensively exploited for cancer therapy." (PMID 30013081, 2018). "PARP1 deficiency, resulting from administration of CDK4/6 inhibitors, impairs OGG1-dependent BER and sensitizes cancer cells to oxidative imbalance-induced death." (PMID 29306194, 2018). "Another cancer-related activity of PARP1 is its recruitment of a SNF2 family member (known as “amplified in liver cancer 1” (ALC1) gene) to DNA26." (PMID 30271949, 2018). "PARP1 inhibitors selectivity kill cancer cells with defects in the homologous recombination repair pathway." (PMID 30463505, 2018). "In contrast, cancer cells with intact HR pathways repair DSBs and show resistance to PARP1 inhibitors." (PMID 29967475, 2018). "A range of small-molecule inhibitors of PARP-1/2, including the inhibitor used here, have been developed for clinical application as they sensitize cancer cells to cell death." (PMID 30157956, 2018).
cancer (continued). "Small-molecule inhibitors of PARP-1/2 activity have been pursued as cancer therapeutics in more than 300 FDA-approved clinical trials." (PMID 30157956, 2018). "Our reported observation that PARP1 and EZH2 interact after DNA damage bear important translational consequences as PARP1 inhibitors are currently used to treat cancer." (PMID 29535829, 2018). "PARP‐1 holds major functions on chromatin, DNA damage repair and transcriptional regulation, both of which are relevant in the context of cancer." (PMID 30467127, 2018). "Downregulation of PARP1 made cancer cells vulnerable to death triggered by the anticancer drugs (WP631 and etoposide) and H2O2." (PMID 29306194, 2018). "Recently, it has been reported that some lncRNAs regulate cancer progression through interaction with PARP1." (PMID 29776974, 2018). "PARP1 inhibitors are used in cancer therapies in the setting of BRCA1 (breast cancer type 1 susceptibility protein) or BRCA2 (breast cancer type 2 susceptibility protein) loss (olaparib and rucaparib approved by FDA in patients with HR dysfunction)." (PMID 29306194, 2018). "The cancer drug target poly(ADP-ribose) polymerase 1 (PARP1) DNA repair enzyme has five pan-PARP probes that are recommended by the Chemical Probes Portal." (PMID 29249694, 2018). "PARP-1 cleavage induced by derivative compounds of EOs contributes to the change of the DNA repair process in the cancer cells." (PMID 30190788, 2018). "RBBP8/CtIP has a proven role in homologous recombination-mediated DNA double-strand break repair known to sensitize cancer cells for PARP1 inhibitors." (PMID 29445424, 2018). "Until today, a variety of PARP1 inhibitor has been developed and clinically used for ovarian, breast and other carcinomas with promising efficiency, and furthermore, new inhibitors such as veliparib and talazoparib have been entered clinical trials." (PMID 29738496, 2018). "Although involvement of such mechanism in neuronal cells or by cocaine has not been previously reported, post-transcriptional regulation of PARP-1 has been documented in cancer cells." (PMID 28828398, 2017). "Next, we transfected SLC6A9 encapsulated plasmid into cancer cells, and PARP-1 was found to be positively correlated with SLC6A9 expression." (PMID 28086241, 2017). "PARP1 modulates the cancer cellular life cycle via regulating cellular mitosis and cell death pathways, including apoptosis, necrosis, and necroptosis." (PMID 28991194, 2017). "PARP1 inhibitors can further suppress the DNA repair process and drive cancer cell death, subsequently inhibiting cancers independently, or as anticancer assistant agents." (PMID 28991194, 2017). "Our work supports the further clinical development of MPH as a novel PARP1/2 inhibitor for cancer therapy." (PMID 27926532, 2017). "Advances in understanding how and where, at a molecular level, these agents function optimally as cytotoxic agents and the recent progress in developing the best reagents are particularly important for the future use of PARP1 inhibitors in cancer therapy." (PMID 28820388, 2017). "Recently, it was found that PARP1 presented high expression in a series of cancers, which provided a high-value target for the study of tumor detection, stage and biological characteristics." (PMID 29152079, 2017). "Both KIF4A and its binding proteins such as PARP-1, BRCA2 and PRC1 have been implicated in multiple types of human cancers." (PMID 28160558, 2017). "PARP1 encompasses several functional domains: three zinc-finger domains (Zn1, 2, and 3), a nuclear localization signal region, a breast cancer suppressor protein-1 domain (BRCT), a WGR domain (automodification domain), and the catalytic PARP domain." (PMID 29387452, 2017).
cancer (continued). "Meanwhile, poly ADP-ribose polymerase-1 (PARP-1) is critical to DNA repair and PARP-1 inhibition has been demonstrated as an effective method for inducing synthetic lethality in cancers depending on PARP-1 activity for survival." (PMID 29564391, 2017). "In this paper, the structure, expression, and functions of PARP1 in cancers will be reviewed, followed by the presentation and analysis of some mature PARP1 inhibitors against human malignancies." (PMID 28991194, 2017). "We investigated the metabolic and mechanistic processes that regulate PARP-1-mediated CTCF PARylation in human cancer cell lines and discovered a key role for the expression and activity of β-NAD+ salvage enzymes, NAMPT and NMNAT-1." (PMID 29029387, 2017). "In summary, CDK12 inhibitors show promise as anti-cancer drugs, either as a stand-alone treatment or in combination with other compounds such as PARP1/2 inhibitors." (PMID 29090014, 2017). "As described, SLC6A9 was identified to promote PARP-1 expression and subsequently lead to cancer cell apoptosis under excessive DNA repair and 131I exposure." (PMID 28086241, 2017). "Chromatid scattering was observed in various cancer cell lines and was correlated with PARP1 and PARP2 expression levels." (PMID 29262611, 2017). "In many types of cancer cells PARP-1 activity and expression are upregulated and essential to support cell survival and promote the aberrant proliferative phenotype." (PMID 29029387, 2017). "The overexpression of PARP1 results from much DNA damage in cancer cells with unstable genes, instead of the induction of the activated specific carcinogenic pathway." (PMID 29152079, 2017). "The earliest discovered PARP1 inhibitors included nicotinamide/ benzamide derivatives, which repress PARP1-induced DNA repair and improve the sensitivity of cancer cells to DNA damaging agents." (PMID 28991194, 2017). "As a PAR-dependent E3 ubiquitin ligase, RNF146 is involved in the beta-catenin signaling pathway in cancer and PARP1 downstream signaling in neuronal death." (PMID 29290984, 2017). "Another major class of cancer drugs includes poly(ADP-ribose) polymerase 1 (PARP1) inhibitors that inhibit PARP1 proteins, which are crucial to repairing single strand breaks in DNA." (PMID 28587102, 2017). "Clinically, PARP1 inhibitors are a very exciting spectrum of drugs that are currently used in cancer management." (PMID 28820388, 2017). "Expression levels of the PARP1 enzyme are significantly elevated in a variety of cancer types compared with normal tissues, due to genomic stress, rapid proliferation, and abnormal metabolism." (PMID 28058462, 2017). "We used nucleoside analogs, a platinum-based DNA intercalator, a topoisomerase IIα poison, and a poly-ADP-ribose polymerase-1 (PARP1) inhibitor that are all approved for the treatment of human cancers in combination with other agents." (PMID 28467801, 2017). "PARP-1 is a nuclear enzyme; just a small PARP-1 fraction has rarely been localized in the cytoplasm of cancer cells." (PMID 28503382, 2017). "Inhibitors of Tdp1, together with its activator, PARP1, and topoisomerase I inhibitors are considered viable drugs in cancer therapy." (PMID 28182794, 2017). "Inhibitors targeting cellular DDR proteins are valid candidates for cancer therapy; for example, the PARP1 inhibitor ABT-888 is in clinical trials." (PMID 28182794, 2017). "PARP1 trapping at DNA lesion by pharmacological inhibitors has been exploited in several cancers exhibiting defects in DNA repair mechanisms." (PMID 28993682, 2017). "The critical role of Parp-1 in maintenance of genomic stability is reflected in its frequent upregulation in cancer, and by hypersensitivity of Parp-1 null animals toward the mutagenic effect of DNA damaging agents." (PMID 29254138, 2017). "AD is a central regulating domain, mainly containing a breast-cancer-susceptibility protein-carboxy terminus (BRCT) motif for auto-ADP ribosylation and mediating PARP1–protein interaction." (PMID 28991194, 2017).